RNU6-98P (RNA, U6 small nuclear 98, pseudogene)
Gene: Small nuclear RNA gene on chromosome X (132,580,117 to 132,580,223, reverse strand). Ensembl gene ENSG00000206900.
Homologues: Orthologues: chimpanzee U6 (100% identical), rat LOC120099392 (83% identical), rat LOC120101953 (82% identical), dog U6 (80% identical), mouse Gm26104 (80% identical), dog U6 (79% identical), rabbit U6 (77% identical), dog U6 (76% identical), pig U6 (71% identical). Paralogues in human: RNU6-1 (90% identical), RNU6-11P (90% identical), RNU6-2 (90% identical), RNU6-37P (90% identical), RNU6-3P (90% identical), RNU6-4P (90% identical), RNU6-5P (90% identical), RNU6-6P (90% identical), RNU6-7 (90% identical), RNU6-8 (90% identical), RNU6-9 (90% identical), RNU6-12P (89% identical), and 1284 more.